PPARGC1A (PPARG coactivator 1 alpha)
Diseases named in the same sentence as PPARGC1A in open-access papers (continued):
Sharing a sentence is not in itself a finding about the gene and the disease.
diabetes (continued). "Furthermore, diabetes-induced impairments of glycolytic rate and mitochondrial function were normalized in diabetic PPKM2Tg glomeruli, in concordance with elevated Ppargc1a and Vegf expressions." (PMID 35133981, 2022). "Thus, similar to the findings in Prkca gene deletion settings, PPARGC1A overexpression ameliorates diabetes-induced NTD formation." (PMID 28474670, 2017). "The reduction in converting LC3-I to LC3-II by diabetes was abrogated in PPARGC1A+ embryos." (PMID 28474670, 2017). "On this basis, we suspected that UA may also modify the transcription of PPARGC1A which further regulate the morbidity of diabetes mellitus." (PMID 25302081, 2014). "It has been reported that the expression levels of PPARGC1A, as well as its downstream target genes was decreased in skeletal muscle of the elderlies and that mRNA levels were decreased in various atrophic states, such as denervation, reduced loading, and type 2 diabetes mellitus." (PMID 40623060, 2025). "Moreover, endothelial PPARGC1A has been found to repress endothelial migration, thus potently inhibit endothelial function and angiogenesis, which further contribute to multiple aspects of vascular dysfunction in diabetes." (PMID 25302081, 2014). "Diabetes-increased p-PERK, p-eIF2α, p-IRE1α and CHOP abundance, ER chaperone gene expression and XBP1 cleavage were abrogated in PPARGC1A+ embryos." (PMID 28474670, 2017). "In our study, PPARGC1A was significantly downregulated in the type IIA myonuclei of the control group after the HIIT intervention, whereas in the diabetes group, it was downregulated in the type I myonuclei, again suggesting different response mechanisms to HIIT for individuals with type 2 diabetes." (PMID 40413649, 2025). "Results indicated that PPARGC1A Gly482Ser led to high BMI in the Tongans population but was unrelated to the onset of type 2 diabetes mellitus, but this was not the case in the Maori population." (PMID 36292779, 2022). "Expressions of mitochondrial-related genes Ppargc1a (PGC1α), cytochrome b component of complex protein III (mt-Cytb), Opa1, and Ndufa9 (a component of complex protein I) were all reduced significantly by diabetes." (PMID 35133981, 2022). "However, it has been shown that PPARGC1A and PRKAR1A are changed in spermatozoa of type 2 diabetes mellitus patients." (PMID 34071734, 2021). "PPARGC1A expression is down-regulated in skeletal muscle from individuals that have impaired glucose tolerance or diabetes, while healthy men exposed to a high-fat overfeeding (HFO) diet for 5 days show increased DNA methylation at the PPARGC1A promoter in both adipose tissue and skeletal muscle." (PMID 31451874, 2019). "Moreover, in muscle, decreased expression of PPARGC1A was observed in diabetes cases and even in non-diabetic individuals with a family history of diabetes." (PMID 28418876, 2017).
type 2 diabetes (168 papers, 2008 to 2026). "In conclusion, altered expression of PPARGC1A is associated with disturbances in BCAA metabolism in skeletal muscle of individuals with type 2 diabetes." (PMID 34131782, 2021). "The aim of this study was to assess the differences in correlation of PPARGC1A polymorphisms with type 2 diabetes (T2D) risk in adults of African origins: African Americans and Haitian Americans." (PMID 25977930, 2015). "For type 2 diabetes it was shown that Gly482Ser polymorphism of PGC-1alpha (encoded by PPARGC1A) was associated with a lower plasma adiponectin level in type 2 diabetic men but not in type 2 diabetic women." (PMID 22809392, 2012). "Meanwhile, decreased expression of PPARGC1A in skeletal muscle has been associated with an increased risk for type II diabetes." (PMID 19077249, 2008). "Peroxisome proliferator-activated receptor gamma coactivator-1 alpha (PPARGC1A) is a multiple-function transcriptional coactivator that has been identified to be associated with many human diseases, such as type II diabetes mellitus, coronary disease, and other diet-related diseases." (PMID 29361788, 2018). "A review reported that environmental factors such as age, gender, obesity, physical activity, and work stress can lead to DNA methylation modification in some genes (for example PPARGC1A, TNF, FTO, LEP, KCNQ1, etc.)that increase the risk of type 2 diabetes." (PMID 39060963, 2024). "In human skeletal muscle, we observed that markers of oxidative fibers and mitochondria correlated positively with expression levels of PPARGC1A and CDK4 and negatively with expression levels of CDKN2A, a locus significantly associated with type 2 diabetes." (PMID 37395281, 2023). "It is possible that PPARGC1A genetic variation, which is also associated with Parkinson’s disease, CHD, and type 2 diabetes can affect its binding with target transcription factors and thus expression of many genes, including APOE." (PMID 37666928, 2023). "Methylation in CpG sites of the PPARGC1A gene (encoding PGC1-α) has been associated with adiposity, insulin secretion/sensitivity indexes and type 2 diabetes." (PMID 32933059, 2020). "Our study revealed a decrease in PPARGC1a, a marker of diminished mitochondrial activity during dietary-induced type 2 diabetes, in the brain of mice housed on the high-fat/high-cholesterol diet." (PMID 28685102, 2017). "Prevention of Ppargc1a overexpression in islets of type 2 diabetes models or in response to glucolipotoxity improve islet function, yet its total knock out in islet beta-cells causes impaired islet function suggesting complex important roles for this co-activator in islet beta-cells." (PMID 35069446, 2021). "Expression of PPARGC1A, which encodes PGC-1α, was decreased in skeletal muscle of individuals with type 2 diabetes, irrespective of the feeding status." (PMID 34131782, 2021). "In accordance, human with Type II diabetes presented reduced expression of Ppargc1a." (PMID 32580324, 2020). "Thus, this study was designed to evaluate the Gly482Ser polymorphism (rs8192678) within the PPARGC1A gene and its association with the increased risk of NAFLD in Iranian patients with type 2 diabetes." (PMID 31390852, 2019). "Validated methylation changes were identified in the promoters of known type 2 diabetes-related genes, including PPARGC1A in muscle (13.9±6.2% vs. 9.0±4.5%, P = 0.03) and HNF4A in adipose tissue (75.2±3.8% vs. 70.5±3.7%, P<0.001) which had increased methylation in type 2 diabetic individuals." (PMID 23251491, 2012). "Increasing evidence suggests that PPARGC1A is involved in the pathogenesis of type 2 diabetes by playing a pivotal role in the control of genetic pathways that result in homeostatic glucose utilization in liver and muscle, beta cell insulin secretion and mitochondrial biogenesis." (PMID 18523557, 2008).
type 2 diabetes (continued). "In addition, the association between PPARGC1A gene rs8192678 C>T polymorphism and CMR has been slightly studied through individual cardiovascular risk factors such as body composition, type 2 diabetes-related parameters, inflammatory markers and lipid profile, and blood pressure." (PMID 35936915, 2022). "In contrast, PPARGC1A was relatively more highly expressed in type IIA myonuclei, but relatively less expressed in type I myonuclei in the untrained leg in the controls compared to type 2 diabetes." (PMID 40413649, 2025). "Given that Klotho ameliorated abnormal lipid metabolism in the liver by upregulating PPARA expression in type 2 diabetic mice, our results suggest that Klotho may improve fatty acid oxidation by regulating PPARA and PPARGC1A expression." (PMID 38584258, 2024). "Experimental approaches to reduce PPARGC1A levels partially recapitulates the BCAA gene set profile identified in skeletal muscle from individuals with type 2 diabetes, without impacting circulating and intramuscular BCAA levels." (PMID 34131782, 2021). "It has been reported that peroxisome proliferator-activated receptor gamma (PPARG) and peroxisome proliferator-activated receptor gamma co-activator 1 (PPARGC1) family (e.g. PPARGC1A and PPARGC1B) are key agents in the development and pathophysiology of type 2 diabetes mellitus (T2DM)." (PMID 28418876, 2017). "In addition, PPARGC1A was positively correlated with BCAA gene expression and BCAA metabolites in individuals with NGT but not type 2 diabetes, while the expression of several BCAA genes was inversely associated with blood glucose and HbA1c." (PMID 34131782, 2021).
melanoma (153 papers, 2013 to 2026). A malignant, usually aggressive tumor composed of atypical, neoplastic melanocytes. "Previous study showed that PGC1-α (PPARGC1A) suppressed melanoma metastasis, and that high PGC1α expression is associated with worse prognosis in metastatic melanomas, and that high GARBD expression is associated with poor survival." (PMID 37020539, 2023). "MITF is closely associated with plasticity in melanoma, and reportedly regulates PPARGC1A (also known as PGC1A), which in turn has a net effect of shifting metabolism towards oxidative phosphorylation." (PMID 34831420, 2021). "The TFE3-related transcription factor MITF was shown to drive OxPhos in melanoma through regulation of PPARGC1A, but also the non-coding RNAs SAMMSON and LENOX." (PMID 40148585, 2025). "For example, enhanced expression of PPARGC1A triggers mitochondrial oxidative metabolism providing chemoresistance in melanoma cells." (PMID 38447939, 2024). "Higher PPARGC1A activity triggers melanocyte inducing transcription factor expression, promoting a melanoma subtype; PPARGC1A protects cancer cells from ROS-induced apoptosis, supporting cancer growth and progression in melanomas." (PMID 38447939, 2024). "Collectively, these results suggest that in a subset of melanoma cells, chronic BRAF inhibitor treatment can cause epigenetic adaptation that involves PPARGC1A suppression and acquisition of aggressive melanoma traits." (PMID 37277330, 2023). "Chronic PLX4032 treated G361 and SKMEL5, however, yielded resistant cells with elevated PPARGC1A expression, which parallels the other end of the change-in-expression continuum seen across melanoma biopsies pre-/post-BRAF inhibitor treatment." (PMID 37277330, 2023). "Collectively these data suggest that the aggressive melanoma phenotypic traits were dependent on PPARGC1A suppression as a result of chronic BRAF inhibitor treatment, which is consistent with our prior studies." (PMID 37277330, 2023). "Oxidative phosphorylation has been shown to promote primary melanoma invasion, suggesting the possible role of PPARGC1A in metabolic rewiring during melanoma progression." (PMID 33937086, 2021). "In melanoma cells, downregulating PPARGC1A/PPARGC1B results in decreased OXPHOS activity, creating an acidic tumor environment and triggering autophagy." (PMID 33937013, 2021). "Multiple promoters of PPARGC1A, a gene encoding PGC1α, are selectively responsive in distinct tissues, and MITF was found to directly stimulate the expression of PGC1α by binding to its promoter region in melanoma cells." (PMID 31461993, 2019). "However, the opposite results have been observed in some other studies, and PPARGC1A has been suggested as a tumor suppressor that suppresses prostate cancer and melanoma cell proliferation, migration, and metastasis." (PMID 33251144, 2020). "Notably, PPARGC1A gene coding PGC-1α is also down-regulated in melanoma." (PMID 36834531, 2023). "Thus, studies of melanoma derived cell lines found subsets of cells with much higher Peroxisome Proliferator-activated Receptor Gamma Co-activator 1-alpha (PGC-1α or PPARγC1α ) protein levels and increased mitochondrial energy metabolism (increased CI-CIV respiratory chain protein contents)." (PMID 25688484, 2015). "Similarly, PPARGC1A (PGC1A), a master regulator of mitochondrial biogenesis regulated by MITF in melanoma, also displayed multiple TFE3 fusion binding sites at the promoter and putative upstream and downstream regulatory elements in the tRCC lines." (PMID 40148585, 2025).
melanoma (continued). "Since PPARGC1A silencing is expected to alter metabolic demands through impeding mitochondrial biogenesis, we used a metabolism-focused compound library to seek differential sensitivity between parental (drug naïve) and chronic treated BRAF-inhibitor resistant K029A melanoma cells." (PMID 37277330, 2023).
breast carcinoma (145 papers, 2009 to 2025). "To our knowledge, this is the first and largest WGS study of BRCA1/2 modifiers to date, and we report PPARGC1A as a novel putative genetic modifier of ovarian and breast cancer risk for BRCA1/2 carriers." (PMID 35625955, 2022). "The expression of PGC-1α, encoded by PPARGC1A, is controlled by the β-catenin pathway in ER+ breast cancer cells." (PMID 36114448, 2022). "Mutations in the PPARGC1A gene have been detected, a specific polymorphism (Thr612Met) has been associated with some classes of breast cancer, and numerous polymorphisms have been linked to ovarian cancer susceptibility." (PMID 29629336, 2018). "While previous candidate gene studies of common genetic variants linked PPARGC1A with ovarian cancer and familial breast cancer risk, our WGS study, focusing on rare and functional variants, was the first to reveal the effect of PPARGC1A in the context of BRCA1/2 mutation." (PMID 35625955, 2022). "PPARGC1A is elevated in breast cancer metastases and is upregulated in the metastases from various primary tumors to liver and peritoneum." (PMID 38039408, 2023). "Studies have shown that PPARGC1A promotes breast cancer metastasis and is upregulated and promotes lung cancer metastasis." (PMID 37023088, 2023). "A future sequencing study of the entire PPARGC1A locus in large ovarian and breast cancer cohorts, particularly in cancer patients with family history, is warranted to further validate our finding of PPARGC1A as a BRCA1/2 genetic modifier." (PMID 35625955, 2022). "Genetic variants in PPARGC1A and PPARGC1B have been reported in breast tumors and were associated with familial breast cancer susceptibility." (PMID 33224957, 2020). "We examined the expression of PGC-1α (PPARGC1A) and glutamine enzymes in 732 breast cancer patients from The Cancer Genome Atlas (TCGA) to determine their expression pattern across breast cancer subtypes and correlation with survival." (PMID 24304688, 2013). "“Associations of genetic variants in the estrogen receptor coactivators PPARGC1A, PPARGC1B and EP300 with familial breast cancer”." (PMID 23216862, 2012). "Our independent validation in PCAWG observed a similar trend of a higher PPARGC1A mutation rate in BRCA carriers than non-carriers for patients with breast cancer." (PMID 35625955, 2022). "In PCAWG’s breast cancer cohort, we observed a trend of higher PPARGC1A mutation frequency in BRCA carriers than non-carriers." (PMID 35625955, 2022). "It is notable that AKR1B10 expression in human breast cancers positively correlated with PPARGC1A." (PMID 34217300, 2021). "Moreover, PPARGC1A high expression was correlated to poor prognosis in patients with lung cancer and breast cancer." (PMID 33251144, 2020). "Recent studies have also revealed that leptin decreases the cytotoxicity of NK cells against breast cancer cells by upregulating PPARG coactivator 1 alpha (PGC1α), suggesting that targeting leptin or PGC1α could enhance NK-based immunotherapy against breast cancer." (PMID 40303301, 2025). "However, the molecular mechanism of AKR1B10 promoting FAO in breast cancer metastasis via PPARGC1A remains unclear." (PMID 34217300, 2021). "Oncoprint analysis revealed genetic alterations in FABP4 (14%), ADIPOQ (2.9%), PPARG (2.8%), PPARGC1A (1.5%), CD36 (1.7%), and CREBBP (11%) in patients with breast cancer in a TCGA study." (PMID 36114448, 2022). "Oncoprint analysis revealed genetic alterations in FABP4 (14%), ADIPOQ (2.9%), PPARG (2.8%), PPARGC1A (1.5%), CD36 (1.7%), and CREBBP (11%) in patients with breast cancer in the TCGA study." (PMID 36114448, 2022). "This study explored the potential targets of RGZ as antiangiogenic agents in breast cancer therapy and highlighted FABP4, ADIPOQ, PPARG, PPARGC1A, CD36, and CREBBP as potential targets of RGZ." (PMID 36114448, 2022).
breast carcinoma (continued). "DNA methylation analysis revealed that the predictive significance of FABP4, ADIPOQ, PPARG, PPARGC1A, CD36, and CREBBP in a specific CpG was significant in the emergence of breast cancer." (PMID 36114448, 2022). "Oncoprint analysis showed genetic alterations in FABP4 (14%), ADIPOQ (2.9%), PPARG (2.8%), PPARGC1A (1.5%), CD36 (1.7%), and CREBBP (11%) in patients with breast cancer in a TCGA study." (PMID 36114448, 2022). "PPARGC1A can promote tumor metastasis by promoting oxidative phosphorylation, while PPARGC1B can promote the proliferation of HER2-overexpressed breast cancer cells." (PMID 36177002, 2022). "We demonstrated a heatmap and prognostic value of DNA methylation clustering of the expression levels of FABP4, ADIPOQ, PPARG, PPARGC1A, CD36, and CREBBP in breast cancer." (PMID 36114448, 2022). "Patients with breast cancer who had low mRNA levels of FABP4, ADIPOQ, PPARG, and PPARGC1A had lower overall survival rates than those with high mRNA levels, which was supported by the overall survival related to DNA methylation." (PMID 36114448, 2022). "Overexpression of PPARGC1A increases the amount of the OXPHOS protein complex, accelerates autophagy, and activates tumor development in breast cancer cells." (PMID 33937013, 2021). "PPARGC1A expression was highest in basal and ERBB2-enriched breast cancer subtypes, which have poorer prognosis than luminal A and B subtypes." (PMID 24304688, 2013). "The expression of glutamine enzymes (glutamine cluster) was positively correlated with PPARGC1A expression in the basal and ERBB2-enriched breast cancer subtypes, in agreement with the fact that these subtypes have the highest expression of PPARGC1A." (PMID 24304688, 2013). "The mRNA expression levels of FABP4, ADIPOQ, PPARG, CD36, and PPARGC1A were significantly lower in patients with breast cancer, whereas the mRNA levels of CREBBP were not different between patients with breast cancer and normal breast tissues." (PMID 36114448, 2022). "The interaction term remained significant when restricting on breast cancer patients, but not in a regression model on the smaller cohort of ovarian cancer patients, where only one patient carried both BRCA and PPARGC1A mutations." (PMID 35625955, 2022). "Analysis of the prognostic value related to TR expression showed that patients with breast cancer with low mRNA expression levels of FABP4 (log-rank P = 0.012), ADIPOQ (log-rank P = 0.01), PPARG (log-rank P = 0.00013), and PPARGC1A (log-rank P = 0.02) had worse OS than those with high mRNA levels." (PMID 36114448, 2022). "The mRNA levels of FABP4, ADIPOQ, PPARG, CD36, and PPARGC1A were significantly lower in patients with breast cancer than in those without breast cancer." (PMID 36114448, 2022). "Invasive cancer cells use the transcription coactivator peroxisome proliferator-activated receptor gamma, coactivator 1 alpha (PPARGC1A, also known as PGC-1α) to enhance mitochondrial biogenesis and OXPHOS, being an essential event for functional motility and metastasis in breast cancer cells." (PMID 34733852, 2021). "Additionally, BPS upregulates genes (THBS4, PPARGC1A, CREB5, COL5A3) related to breast cancer progression." (PMID 33330580, 2020). "We performed semi-quantitative real-time reverse transcriptase PCR of all candidate genes but only PPARGC1A showed successful validation by being stabilised in individuals with breast cancer but not in many unaffected members of the same family." (PMID 22703186, 2012). "In addition, PPARGC1A was found to be differentially expressed between BRCA carriers and non-carriers within the TCGA breast cancer cohort." (PMID 35625955, 2022).